DLL1 (delta like canonical Notch ligand 1)
Diseases named in the same sentence as DLL1 in open-access papers (continued):
Sharing a sentence is not in itself a finding about the gene and the disease.
tumor (continued). "DLL1-mediated NOTCH signaling is activated to promote the expression of CD16 and killer Ig-like receptors that are important for cytotoxicity against tumor cell." (PMID 37893184, 2023). "The ligands DLL1, DLL4, JAG1, and JAG2 each activate Notch receptor signaling, as DLL1 and DLL4 are involved in tumor angiogenesis." (PMID 37274780, 2023). "Several of these EPINs have promoters of differentially expressed genes (such as DLL1, STOM and SEC11C in the GEPIA tumor/normal dataset; ID2, RPS27, SEC11C, CASZ1, CRTC2, C5 and STOM in the LNCaP/LHSAR dataset; see Methods, Differential Gene Expression)." (PMID 38057321, 2023). "It has been described a dual role for the Notch receptor (Notch 1–4)-ligand (JAG1, JAG2, DLL1, DLL3 and DLL4) pathways as oncogenic or tumor suppressors." (PMID 36745330, 2023). "Overexpressing DLL1 in bone marrow progenitor cells can also activated CD8+ T cells and inhibit fibrosarcoma tumor growth." (PMID 36008793, 2022). "Selective activation of Delta-like 1 (DLL1)-Notch signaling is a new approach to activate CD8+ T cell and suppress tumor growth, while the efficacy remains modest." (PMID 36008793, 2022). "Flow cytometric analysis showed that DLL1 overexpression alone increased intratumoral CD8+ T cells, and EO771-L1 tumor with LNT treatments had the highest percentage of intratumoral CD8+ T cells." (PMID 36008793, 2022). "In contrast, the interaction scores of DLL4-NOTCH3, DLL1-NOTCH1, TGFBR3-TGFB1, and IGF1R-IGF1 between tumor cells and endothelial cells increased after treatment." (PMID 36474268, 2022). "Thus, we hypothesized that LNT treatments improve tumor growth inhibition of DLL1 via neutrophils." (PMID 36008793, 2022). "Remarkably, LNT treatments synergistically enhanced the suppression of DLL1 on LAP0297 lung tumor growth, resulting in tumor regression." (PMID 36008793, 2022). "In a mouse model with CD11c lineage-specific deletion of Dll1, CD8+ T cells are decreased, while regulatory T cells (Tregs) and myeloid-derived suppressor cells (MDSCs) are increased, leading to faster tumor growth." (PMID 35332121, 2022). "We then performed the immunohistochemical (IHC) staining of DLL1, a representative protein in the Notch signaling pathway, and NCAM1, a representative protein of infiltrating natural killer cells, in the tumor tissues of 8 patients." (PMID 34857809, 2021). "MPDZ modulates DLL4-induced Notch signaling in the vasculature through physical interaction with DLL1 and DLL4, assisting their interaction with the adherents junction protein Nectin-2 and improving Notch signaling activity with tumor angiogenesis drop off." (PMID 34440260, 2021). "To further investigate the mechanistic basis of Dll1-mediated effect on metastasis and cell survival of tumor cells, we performed ATAC-seq to examine the chromatin accessible and restricted regions in Dll1+ and Dll1− tumor cells." (PMID 33462238, 2021). "It has been shown that in BCC tumor regions, the expression of NOTCH1, DLL1 and JAG1 is lowered in comparison to physiological healthy regions, the basal layer." (PMID 32796631, 2020). "The deletion of either one or two alleles of Dll1 resulted in a moderate increase in total cell counts of tissue-resident CD11b+CD11c+ DC populations in the tumor or spleen compared to wild-type littermates, but ability of DCs to undergo maturation or infiltrate the tumor was not affected." (PMID 30940183, 2019). "To delineate how Dll1 promotes luminal tumor growth and progression, we assessed Ki67 expression, a marker of cell proliferation, in MCF7 and WTB tumor sections." (PMID 30442981, 2019). "miR-34a was also reported to target Notch signaling pathway to inhibit tumor stem cell invasion by directly binding to NOTCH1, DLL1 and JAG1 as well as Wnt signaling pathway by targeting WNT1 and WNT3 genes and TGF-β signaling pathway via Smad4." (PMID 23823624, 2013). "The three proteins DLL1, FOXO1 and p27 were exclusively expressed by the T14 RB tumor cells." (PMID 39695086, 2024).
tumor (continued). "Mechanical analysis revealed that in vivo knockout of CD8+ T cells or silence of IFN-γ reversed the suppression of tumor growth and attenuated DLL1-mediated vascular normalization without influencing DLL1-induced macrophage polarization." (PMID 36439137, 2022). "Elevated DLL1 levels in the TME activated CD8+ T cells and slowed down tumor growth." (PMID 36008793, 2022). "Since DLL1 promotes tumor cell proliferation, and Dl1.72 decreases MCF-7 cell proliferation in vitro, we assessed tumor cell proliferation in tumor sections stained with Ki67 antibody." (PMID 34439228, 2021). "Using conditional-knockout mice of Dll1, we further demonstrated that Dll1 has a significant tumor-promoting function in MMTV-PyMT tumors but not in MMTV-Wnt1 tumors." (PMID 33462238, 2021). "Indeed, further analysis of transplanted tumors revealed that Dll1+ tumors were less prone to cell death compared to Dll1− tumors as seen by cleaved-caspase-3 and TUNEL staining (apoptotic cells) in the tumor cells." (PMID 33462238, 2021). "In conclusion, the present study describes the development and characterization of a novel anti-DLL1 mAb with potent anti-tumor activity in an ER+ BC mouse model, without detectable side effects." (PMID 34439228, 2021). "Especially, combination treatment of Dll1 antibody, IMD and chemotherapy further decreased the number and size of tumorspheres, while either IMD or chemotherapy alone had minimum effect on tumor cells." (PMID 33462238, 2021). "Preferential expression of Jagged1 and Jagged2 ligands, but not Dll1 and Dll4, was detected in tumor-infiltrating MDSCs." (PMID 33585446, 2020). "This is illustrated for example by studies on tumor initiation (Notch1; Notch3), stem cell control (Notch1; Notch4; Jag1; Jag2; DLL1), angiogenesis (Notch1; DLL4) invasion and metastasis in remote organs (Notch1; Notch2; Jag1; DLL1)." (PMID 32605277, 2020). "Previous studies showed that altered expression of Notch ligands could underlie immunosuppression in cancer, and in particular, expression of Delta-like ligands DLL1 and DLL4 was significantly down-regulated in tumor-bearing hosts." (PMID 30940183, 2019). "Notably, MCF7 DLL1-KDs had significantly reduced BLI signals in the lungs compared to control, indicating fewer tumor cells in the metastatic site." (PMID 30442981, 2019). "Overall, these results are consistent with reported data indicating that DLL1 promotes tumor growth of luminal BC but not TNBC cells." (PMID 31107884, 2019). "In contrast to mouse luminal tumors, reduced levels of Dll1 in mouse TNBC (4T1) cells show no major difference in tumor growth and metastasis compared to control." (PMID 30442981, 2019). "We performed extensive immunophenotyping of myeloid and lymphoid populations infiltrating the tumors and in spleens of mice with CD11c+ lineage-specific hetero or homozygous deletion of Dll1 and their wild-type littermates on day 17–18 after LLC tumor establishment." (PMID 30940183, 2019). "However, reduction of DLL1 leads to increased metastasis in DLL1-KD1 HCC1806 compared to control, which was further confirmed by injecting tumor cells using a tail-vein metastasis assay." (PMID 30442981, 2019). "Given that DLL1/4 induce TH1 and CTL effector function, this could be an additional mechanism, whereby the tumor microenvironment impairs/disables NOTCH signaling." (PMID 30967879, 2018). "On the other hand, recombinant ligands such as Dll1, Dll4, and JAG1 have been reported to activate Notch signaling in various cell types, including intestinal organoids and tumor spheroids." (PMID 28455349, 2017). "The data suggest that LNT may enhance cancer immunotherapy via modulating neutrophils, while all of increased CD8+ T cells, increased neutrophils and reduced TAMs may contribute to tumor growth inhibition induced by the combination of LNT treatments and DLL1 overexpression." (PMID 36008793, 2022).
tumor (continued). "Our findings indicates that LNT and DLL1 may induce synergistical antitumor immunity via simultaneous modulating lymphoid and myeloid cell populations regardless of the type of tumor, providing a potential new strategy to potentiate cancer immunotherapy." (PMID 36008793, 2022). "In addition to tumor tissues, we also subjected Moc2 EphB4 KO and control cell lines to RNA-seq analysis and observed similar changes in the genes involved in the VEGF signaling pathway including VEGFA, DLL1, NRP2." (PMID 35725568, 2022). "In this study, we used Dll1 conditional knockout and reporter models crossed with spontaneous murine models (MMTV-PyMT and MMTV-Wnt1) to determine the spatial and temporal distribution of Dll1 and also determine the function of Dll1+ tumor cells in tumor progression." (PMID 33462238, 2021). "This is consistent with the hypothesis that the observed alterations in anti-tumor T-cell responses is due to the absence of DLL1 expression on DCs." (PMID 30940183, 2019). "However, it is not yet clear whether the tumor-promoting function of Dll1 on CSCs is also responsible for endocrine resistance." (PMID 35682974, 2022). "However, at that time, we could not evaluate the spatial and temporal distribution of Dll1 expression during tumor progression and metastasis." (PMID 33462238, 2021). "In contrast to the striking effect of Dll1 deletion on IFN-γ production, genetic ablation of Jag2 in DCs did not have a major effect on the number of tumor-infiltrating IFN-γ-producing cells." (PMID 30940183, 2019). "We found that in mice with hetero and homozygous deletion of Dll1 in DCs, the numbers of IFN-γ-producing MUT1-specific lymphocytes were markedly decreased in the tumor, whereas the numbers of tumor-infiltrating IL-4-producing cells were not altered." (PMID 30940183, 2019).
cancer (56 papers, 2008 to 2026). A tumor composed of atypical neoplastic, often pleomorphic cells that invade other tissues. "For instance, delta-like 1 (DLL1), is a ligand of the Notch pathway that is expressed in endothelial cells and has been linked to aberrant vascularization in cancer, acting as a compensator of tumoral hypoxia." (PMID 35565420, 2022). "While the association of NOTCH signaling and NPC pathogenesis remains unclear, our findings is the first to report FBXW7 and DLL1 mutations in this cancer type." (PMID 28256603, 2017). "Specifically, apoptotic cancer cells display increased surface expression of the Notch ligand Delta-like 1 (DLL1), which interacts with Notch1 receptors on CAFs and subsequently drives transcriptional activation of WISP-122." (PMID 41522359, 2026). "Notch pathway negatively impacts the activity of the Wnt pathway in most cancers; Wnt can also impact the expression of DLL1, HES1 and NOTCH2 on the protein level, while β-catenin can also interact with NOTCH1 and reduce its ubiquitination." (PMID 40002854, 2025). "Current research has shown that DLL1 obviously has a crucial impact on tumorigenesis and the development of many cancers." (PMID 36071128, 2022). "Western blot confirmed that Dll1 expression was increased only in lysates of apoptotic cancer cells." (PMID 36241874, 2022). "LNT and DLL1 have been shown to suppress the growth of several types of cancer and the effects have been largely attributed to immune stimulation." (PMID 36008793, 2022). "Dll1 expression was enhanced in UV-irradiated apoptotic cancer cells, including 344SQ, A549, and HCT116 cells." (PMID 36241874, 2022). "The Delta-like ligand 1, DLL1, has been identified as a protein with dual roles in various types of cancer." (PMID 34641286, 2021). "Cellular assays using MCF-7 ER+ BC cells revealed that Dl1.72 impaired DLL1-Notch signaling and reduced cancer cell proliferation and migration as well as the BCSC population." (PMID 34439228, 2021). "Here, the authors show that in breast cells the Notch ligand DLL1 is expressed in cells with a cancer stem cell phenotype and promote doxorubicin resistance in part through NF-kB, as well as metastasis." (PMID 33462238, 2021). "The levels of BIRC5/Survivin, expressed in most human cancers, but absent in normal tissues, and shown to promote proliferation and inhibition of apoptosis of cancer cells including BC, were also significantly reduced by DLL1 downregulation (2-fold)." (PMID 31107884, 2019). "Given that NOTCH2, FBXW7 and DLL1 are key components in NOTCH signaling and have predictive value in cancer therapies, the effect of these mutations in NPC is yet to be elucidated." (PMID 28256603, 2017). "It has been found that mir-34a regulates the expression of NOTCH1 and DLL1 in different types of cancer." (PMID 27039384, 2016). "In another set of experiments, we transiently overexpressed either mouse Jag1-Fc or another Notch ligand relevant in cancer, mouse Dll1-Fc in PC3 cells." (PMID 27749937, 2016). "Since miR-34a suppresses many oncogenes and cancer stem cell markers including CD44, CDK4, CDK6, c-Met, Notch-1, Notch-2, SIRT1 and DLL1 as its target genes, miR-34a plays important roles in cancer stem cells." (PMID 26580663, 2015). "In higher grade and stage cancers, DLL1 was diminished, often heterogeneously expressed and delocalized to the cytoplasm and focally even to nuclei." (PMID 25167871, 2014). "Among the ligands, DELTA1 (DLL1) expression was strongly and significantly decreased in cancer tissues, whereas JAGGED1 (JAG1) and JAGGED2 (JAG2) mRNA levels were not significantly changed." (PMID 25167871, 2014). "In summarizing our study, CD133 was exclusively expressed in cancer cells compared to stromal and immune cells and was associated with other CSC markers (CD24, NOTCH1, DLL1, and ALDH1A1), as well as enriched WNT/β-Catenin, Hedgehog, and NOTCH signaling, validating CD133 as a CSC marker." (PMID 38585981, 2024).
cancer (continued). "We found that among various Notch ligands on UV-irradiated apoptotic cancer cells, Dll1 exhibited enhanced expression, suggesting that an interaction between Dll1 on the surface of apoptotic cancer cells and the Notch1 receptor on CAFs is responsible for most Notch signaling." (PMID 36241874, 2022). "However, interfering with circulating VEGF-induced DLL1-Notch signaling inhibition by overexpressing DLL1 in cancer cells induced long-term vascular normalization." (PMID 35712656, 2022). "Whether LNT combined with DLL1 intervention can enhance the inhibitory effect on the growth of cancers." (PMID 36008793, 2022). "Interestingly, Dll1+ cells were also enriched for signatures of NF-κB signaling and hypoxia, common features of cancer progression and chemoresistance." (PMID 33462238, 2021). "Interestingly, in ovarian cancer, there is evidence that Notch is activated in cancer cells, which are close to the TME and that the small vessels expressing Notch ligands such as Jagged-1 and DLL-1/3/4 are key in regulating Notch signalling in cancer cells." (PMID 32575680, 2020). "To knockdown human DLL1 in these cancer cells, we utilized shRNA/lentivirus approach." (PMID 30442981, 2019). "Since DLL1 has been shown to promote clonogenic growth of cancer cells in vitro, we assessed whether its downregulation could impact the colony formation capability of BC cells." (PMID 31107884, 2019). "However, our findings demonstrating that DLL1 is regulated by p65 also in the cancer cells suggests that reciprocal interactions take place between the two cell types, in a complex manner that requires further investigation." (PMID 31105691, 2019). "Accumulating evidence indicates that DLL1 might be involved in the development and progression of various types of cancer." (PMID 31107884, 2019). "We hypothesized that the Tg6F-mediated increase in Notch1 and Notch 2 with increased Dll4 and Dll1 expression in the jejunum in the cancer model might affect the immune cell repertoire." (PMID 29899427, 2018). "Within the list of top differentially expressed genes, in the UCHL1 KDs we found downregulation of the Wnt targets POSTN, SP7, and DLL1, of the transporter ABCA4, of the homeobox gene DLX4, and of genes recently linked to cancer progression ACTA2, AQ4, GRAP2, and ALK." (PMID 28472177, 2017). "In KG-1α cells, overexpression of DLL1 could partially reverse the biological effect caused by knockdown of MSI2 through restoring the expression levels of the key factors of Notch1 signaling pathway and cancer stemness-related proteins." (PMID 37149661, 2023). "However, the expression of its ligands, Jagged 2 and Dll1, was higher in the carcinoma tumors." (PMID 18811984, 2008). "In HNSC, both expression and DEG enrichment of JAG1, DLL1, and NOTCH2 significantly increased after anti-cancer therapy, while DLL3 and NOTCH4 significantly decreased." (PMID 39074091, 2024). "Both expression and DEG enrichment of JAG1, DLL1, and NOTCH4 significantly increased after anti-cancer therapy in BIC." (PMID 39074091, 2024). "Downregulation of ST6GAL1 decreases Jagged1, DLL-1, Notch1, Hes1, Hey1, MMPs and VEGF, and suppresses cancer cell proliferation, migration and invasion." (PMID 37256139, 2023). "Ligands are also expressed in most human tissues, including cancer tissues: these are the Jagged 1 and 2 proteins (JAG1 and JAG2), and the delta-like ligands (DLL1, DLL3, and DLL4)." (PMID 34944837, 2021). "As there are many Notch ligands—Jag1, Jag2, DLL1, DLL3, and DLL454—we wanted to identify which Notch ligand(s) is/are involved in stemness induction in cancer cells." (PMID 34911937, 2021). "Fringe modulation of ligands will be of significance in understanding Notch activity in cancer stem cell asymmetric division where LFNG, DLL1 and NOTCH1 are present in the same cell." (PMID 29629872, 2018).
cancer (continued). "In contrast, transcripts encoding several canonical Notch signalling components, including DLL1, JAG1, NOTCH1 and HES2, were down-regulated in cancer cells." (PMID 25864518, 2015). "CTNNB1 and FBXW7 genes are some of the most altered Wnt pathway genes in OC, while in the Notch pathway the receptors (NOTCH1-4), ligands (such as DLL1, JAG2), as well as the canonical target (HES1), are some of the most dysregulated Notch genes in cancers overall." (PMID 40002854, 2025). "Across the cancer tissues, expression of HES1 mRNA was significantly increased compared to normal bladder, despite the significant downregulation of NOTCH1, NOTCH2 and DLL1." (PMID 25167871, 2014). "When DLL1 is overexpressed in breast and lung cancer lines, it induces a normal vascularization around the tumor and the activation of CD8+ T cells, which could be useful in cancer immunotherapy, ameliorating the distribution of the antitumoral drugs." (PMID 35565420, 2022). "Interestingly, we observed that DLL1 downregulation considerably increased the mRNA levels of Cyclin D2, a G1/S transition gene, whose expression is very low or absent in some human cancers due to promoter hypermethylation." (PMID 31107884, 2019).